OR11A1 (olfactory receptor family 11 subfamily A member 1)
Description:
Odorant receptor.
Synonyms: OR11A2; hs6M1-18; 6M1-18; dJ994E9.6
Tractability: Small molecule: it belongs to a druggable protein family. Antibody: its Gene Ontology location is reachable by antibodies, with high confidence; UniProt places it where antibodies can reach, with medium confidence; UniProt predicts a signal peptide or a membrane-spanning region.
Gene: Protein-coding gene on chromosome 6 (29,425,504 to 29,457,071, reverse strand). Ensembl gene ENSG00000204694.
Subcellular location: Cell membrane
Pathways (Reactome):
Sensory Perception: Expression and translocation of olfactory receptors; Olfactory Signaling Pathway
Gene Ontology:
Molecular function: G protein-coupled receptor activity; olfactory receptor activity
Biological process: detection of chemical stimulus involved in sensory perception of smell; G protein-coupled receptor signaling pathway
Cellular component: plasma membrane; membrane
Genetic constraint (gnomAD): Loss-of-function variants: 0 observed, 0.84 expected, observed/expected ratio (o/e) 0, 90% interval 0 to 1.76. That is too few expected variants to judge how well the gene tolerates losing a copy. Missense variants: 380 observed, 397.53 expected, observed/expected ratio (o/e) 0.96, 90% interval 0.88 to 1.04. Synonymous variants: 158 observed, 160.5 expected, observed/expected ratio (o/e) 0.98, 90% interval 0.86 to 1.12.
Homologues: Orthologues: chimpanzee OR11A1 (96% identical), macaque OR11A1 (93% identical), rabbit OR11A1 (84% identical), mouse Or11a4 (74% identical), rat Or11a4 (74% identical). Paralogues in human: OR11G2 (45% identical), OR11H4 (45% identical), OR11H2 (43% identical), OR11H1 (43% identical), OR11H12 (43% identical), OR11H6 (43% identical), OR11H7 (42% identical), OR9G1 (40% identical), OR10X1 (36% identical), OR9A4 (35% identical), OR9A2 (34% identical), OR9A1P (33% identical), and 21 more.